EGFR (epidermal growth factor receptor)
Diseases named in the same sentence as EGFR in open-access papers (continued):
Sharing a sentence is not in itself a finding about the gene and the disease.
gliosarcoma (continued). "Gliosarcomas have a similar cytogenetic profile to primary GBM with the exception of epidermal growth factor receptor (EGFR) amplification, which is rare in gliosarcomas, while EGFR is overexpressed in about 50% of GBM cases." (PMID 27699141, 2016). "Many literatures report that the genetic profile of gliosarcoma is similar to that of GBM, except for absent or minimal EGFR amplification and rare cases of IDH mutations." (PMID 34605602, 2021). "In gliosarcoma, no independent trial with EGFR targeted agents has been published to our knowledge." (PMID 34504233, 2021). "Gains of chromosome 7 without EGFR amplification is frequent in gliosarcoma, leading one to believe the oncogenic driver for gliosarcomas may reside on chromosome 7, but not necessarily related to the EGFR pathway." (PMID 31073965, 2019). "Therefore, even though EGFR amplification is not common in gliosarcoma, EGFR pathway activation may still be present." (PMID 31073965, 2019). "Thus, it is unclear whether EGFR pathway activation is present in gliosarcoma; perhaps it is present through indirect mechanisms and not necessarily through overexpression of EGFR due to gene amplification." (PMID 31073965, 2019). "Previous reports show a very low or absent EGFR amplification/overexpression in gliosarcoma tumors, but the recent copy-number analysis using CNV microarrays showed frequent EGFR amplification." (PMID 30818875, 2019).
human papillomavirus infection (17 papers, 2014 to 2025). "The KEGG pathway analysis of SchB against SARS-CoV-2_hepatitis demonstrated a correlation with cancer, EGFR tyrosine kinase inhibitor resistance, cell cycle, human papillomavirus infection, HCV infection, and platinum drug resistance." (PMID 36034788, 2022). "The curability of HNSCC with radiochemotherapy was previously found to be associated with clinical and biological parameters including tumor volume, hypoxia, epidermal growth factor receptor expression, and human papillomavirus infection status." (PMID 33919702, 2021). "Signal pathway analysis of tiRNA5-Lys-CTT-1 showed the tsRNA was involved in the pathway of Human papillomavirus infection, Senescence and Autophagy in Cancer, EGF/EGFR Signaling Pathway." (PMID 36845141, 2023).
invasive ductal carcinomas (17 papers, 2011 to 2026). "The invasive ductal carcinomas group showed a trend toward higher EGFR gene amplification, although the association with tumor type was not statistically significant." (PMID 22132735, 2011). "EGFR amplification is more common in invasive ductal carcinomas (IDC) (1.4-2.9%) compared to invasive lobular carcinomas (ILC) (0-0.6%)." (PMID 40501689, 2025). "The gene data sets 5-LOX activating protein (FLAP), 5-LOX, mPGES-1, mPGES-2, EGFR, and DclK1 were significantly decreased by the combination treatment during the progression of pancreatic lesions to ductal adenocarcinoma." (PMID 26429877, 2015). "Members of the epidermal growth factor receptor (EGFR) family are transmembrane receptors with tyrosine kinase activity and are overexpressed in 20% to 90% of ductal adenocarcinomas." (PMID 25301978, 2014). "Research on the correlation between EGFR expression and CD44/CD24 and their prognostic value in breast invasive ductal carcinoma (BIDC) is limited." (PMID 25429827, 2015). "We studied the correlation between epidermal growth factor receptor (EGFR) and the tumor stem cell markers CD44/CD24 in breast invasive ductal carcinoma (BIDC) and their relationship with prognosis." (PMID 25429827, 2015). "Paraffin-embedded 135 TN invasive ductal carcinoma tissue samples were immunohistochemically investigated using the Dako Envision+ kit and primary antibodies for maspin, basal (CK5/6, EGFR, CK14) and myoepithelial markers (p63, CD10)." (PMID 21496280, 2011).
large cell lung cancer (17 papers, 2012 to 2024). "The occurrence of EGFR mutations in adeno, squamous cell, and large cell lung cancer patients among our sample was 54% (13 samples), 28% (5 samples), and 50% (3 samples)." (PMID 28684733, 2017). "De Pas and colleagues reported a case of lung large cell carcinoma patient harboring EGFR mutation having dramatic response to gefitinib treatment." (PMID 26486077, 2015). "While MMP-2 creates fragments from laminin-332 that increase EGFR and F-actin expression and promote VM in large cell lung cancer, MMP-13 counteracts VM by releasing different laminin-332 fragments that decrease expression of EGFR and F-actin." (PMID 29112161, 2017). "EGFR (15.8%) and KRAS (21.1%) mutations were present in a considerable proportion in lung large cell carcinoma." (PMID 26486077, 2015). "NCCN guidelines recommend EGFR testing for the following histologies upon cancer recurrence or metastases: adenocarcinoma (AC) and large cell lung cancers (LC)." (PMID 22363766, 2012). "Previously, patients with lung non-adenocarcinoma, such as large cell lung carcinomas (LCLCs), harboring EGFR mutations and treated with EGFR-TKIs, also had a reduced mPFS (4.4 months)." (PMID 34195081, 2021). "Rybrevant is a fully human bispecific monoclonal antibody directed at the EGFR and MET receptors and indicated for the treatment of adult patients with specifically large cell lung cancer." (PMID 38910714, 2024). "High levels of EGFR expression were detected in A549, XWLC-05 and H157 cells, but much lower levels of EGFR were detected in large cell lung cancer H460 and non-tumor bronchial epithelial Beas-2b cells." (PMID 29152147, 2017).
neuroendocrine carcinoma (17 papers, 2013 to 2026). A malignant neuroendocrine neoplasm composed of cells containing secretory granules that stain positive for NSE and chromogranin. "EGFR mutations may persist even after transformation into neuroendocrine carcinoma." (PMID 40040728, 2025). "We report the case of a patient affected by advanced EGFR mutation-positive lung who experienced resistance to therapy during treatment with Afatinib through the occurrence of a switch of tumor histotype to small cell lung cancer (SCLC) with features of a G3 neuroendocrine carcinoma." (PMID 28938699, 2017). "In neuroendocrine cancer, EGFR mediated signaling is highly activated, responsible for the disease’s adversity." (PMID 39183332, 2024). "The patient had the EGFR L858R mutation of adenocarcinoma, and developed the rapid drug resistance against TKI probably due to the combination of neuroendocrine carcinoma and adenocarcinoma." (PMID 32508051, 2020). "Among patients with non-small cell lung cancer (NSCLC) who developed resistance to EGFR-TKIs, the pooled proportion of transformation to high-grade neuroendocrine carcinoma (HGNEC) was 6% (95% CI, 5%-8%), while transformation to non-neuroendocrine NSCLC occurred in 2% of cases (95% CI, 2%-3%)." (PMID 42163145, 2026). "Moreover, while the mechanism of adenocarcinoma transformation is relatively well understood, the mechanism by which ASC transforms into a neuroendocrine carcinoma following EGFR-TKI treatment remains to be further explored." (PMID 40040728, 2025). "In neuroendocrine cancer, both MET and EGFR mediated signaling are highly activated, which is responsible for the adversity of the disease." (PMID 38168280, 2023). "The first case highlighted acquired EGFR-TKI resistance through transformation to the high-grade neuroendocrine carcinoma spectrum and that such transformation might not be evident at time of progression on TKI therapy." (PMID 25699082, 2015). "No amplifications were identified in cMET, EGFR, or HER2 by ISH in any neuroendocrine cancer of the ovary." (PMID 27566252, 2016).
non-small cell lung adenocarcinoma (17 papers, 2014 to 2025). Type of epithelial lung cancer arising from glandular origin. "This hotspot mutation, well-described in non-small-cell lung adenocarcinoma, is predictive of the response to EGFR tyrosine kinase inhibitors." (PMID 36980614, 2023). "For instance, detection of plasma-derived EGFR mutation of advanced or metastatic non-small cell lung adenocarcinoma (NSCLC) patients is helpful for the treatment with EGFR tyrosine kinase inhibitors (TKIs)." (PMID 36153611, 2022). "For example, in non-small cell lung adenocarcinoma, the efficacy of tyrosine kinase inhibitors, including gefitinib and erlotinib, is linked to epidermal growth factor receptor (EGFR) mutations, which are much more prevalent among Asian patients than EAs (30% vs. 7%)." (PMID 27246981, 2016). "Our previous work demonstrated that Sorcin regulates EGFR signaling in non-small cell lung adenocarcinoma, promoting cellular invasion and migration." (PMID 41148307, 2025). "The epidermal growth factor receptor (EGFR) gene is one of the most frequently mutated genes in multiple cancers, particularly in non-small cell lung adenocarcinoma." (PMID 36012178, 2022). "In our studies, we also expressed an activated form of EGFR, EGFR(L858R), which occurs in several types of cancer, including non-small-cell lung adenocarcinoma." (PMID 32697994, 2020). "The enrichment of cancer stem cell-like cells (CSCs) has been considered to be responsible for tumor progression after an initial response to epidermal growth factor receptor (EGFR) tyrosine kinase inhibitors (EGFR-TKIs) in patients with non-small cell lung adenocarcinoma (NSCLC/ADC)." (PMID 32293355, 2020). "Similarly, MET knock down sensitized two cetuximab resistant non-small cell lung adenocarcinoma cell lines, LXFA 526 L and LXFA 1647 L, to EGFR inhibition." (PMID 33596979, 2021).
Pruritus (17 papers, 2006 to 2026). Pruritus is an itch or a sensation that makes a person want to scratch. "Pruritus can be present along with the EGFR inhibitor–associated rash; therefore, treatment of the rash can also help to relieve some of the accompanying pruritus." (PMID 25031940, 2012). "Severe cases are rare; however, both EGFR antibodies (cetuximab, 17%; panitumumab, 16–33%) and TKIs (gefitinib, 15.6–63%; erlotinib, 10–42%; afatinib, 10.9–23%; osimertinib, 12–18%; dacomitinib, 10–20.7%) can cause mild pruritus." (PMID 40888993, 2025). "Pruritus and treatment line were independently associated with objective response, suggesting that pruritus may serve as a potential clinical indicator of treatment response and highlighting the importance of monitoring of the EGFR-TKI-related AEs during therapy." (PMID 41899369, 2026). "EGFR inhibitor-induced pruritus rarely occurs during or within 24 h after the administration of chemotherapy, and complaints of generalized pruritus during EFGR inhibitor administration require treatment, assuming that an infusion-related reaction is involved." (PMID 40888993, 2025). "Future studies should be directed at further understanding the mechanism of EGFR-TKI-induced pruritus and skin toxicity in order to better develop pharmacotherapies to relieve symptoms without interfering with cancer treatment." (PMID 31835310, 2019). "Pruritus: Pruritus is common with all of these agents but especially with EGFR inhibitors and checkpoint inhibitors." (PMID 29152401, 2016). "At least 10% of patients receiving EGFR antibodies or TKIs develop pruritus." (PMID 40888993, 2025). "Conversely, in a case series of 20 patients treated with different epidermal growth factor receptor inhibitors in Greece, pimecrolimus cream 1% (substituted by metronidazole 1% cream) was effective in most patients (> 50% reduction of erythema, pustules and pruritus)." (PMID 31444619, 2019). "In summary, our findings demonstrated that aprepitant activated EGFR in human keratinocytes by interacting with NK1R, and this might be the mechanism by which aprepitant reduces erlotinib-induced pruritus and skin toxicity." (PMID 31835310, 2019).
rheumatoid arthritis (17 papers, 2008 to 2025). A chronic, systemic autoimmune disorder characterized by inflammation in the synovial membranes and articular surfaces. "We have previously examined the association of rheumatoid arthritis prevalence and the two EGFR SNP sites (rs2227983 and rs17337023) among Taiwan’s Han Chinese population." (PMID 28700691, 2017). "The analysis of transcription and phosphorylation protein omics of rheumatoid arthritis showed that the change in mitochondrial function was related to the increase in epidermal growth factor receptor (EGFR)-JAK-STAT3 signal transduction." (PMID 38886785, 2024). "Swanson and co-workers demonstrated EGFR overexpression in synovial fibroblasts and endothelial cells, both in patients suffering from rheumatoid arthritis and in a murine model of the pathology." (PMID 29271876, 2017). "Recent studies demonstrate that EGFR is involved also in other severe pathologies, such as rheumatoid arthritis, which is characterized by aberrant cell growth." (PMID 29271876, 2017). "Our results suggest EGFR pathway inhibition may be a promising option to prevent joint destruction in the treatment of rheumatoid arthritis." (PMID 36326383, 2022). "Epidermal growth factor receptor (EGFR) family members and their associated ligands may be related to bone and joint destruction in rheumatoid arthritis." (PMID 36326383, 2022). "Here, we not only reporting the characterization of a SNP variation of EGFR in rheumatoid arthritis patients, but also the EGFR protein levels in RA patient’s serum." (PMID 28700691, 2017). "Leflunomide, an antimetabolite and inhibitor of PDGFR, EGFR and FGFR, is used for the treatment of rheumatoid arthritis." (PMID 33918704, 2021). "Since a role for PAR1-EGFR interplay in rheumatoid arthritis has been suggested it may be worthwhile to test in a clinical study a combination of PAR1 and EGFR antagonists." (PMID 24215724, 2013). "Since synovial hyperplasia in rheumatoid arthritis (RA) resembles a tumor, involvement of the EGF/EGFR families in RA pathology has been implied." (PMID 18439312, 2008).
tongue cancer (17 papers, 2009 to 2025). A malignant neoplasm affecting the tongue. "Three key bioactive compounds in Rumex dentatus (quercetin, taxifolin, and emodin) target 66 common genes linked with cisplatin and tongue cancer, including EGFR, BCL2, and ESR1 as the most important genes identified." (PMID 39863836, 2025). "The poor prognosis of patients with tongue cancer has been shown to be associated with the higher expression of EGFR and its phosphorylated form (EGFRP) in tumor samples." (PMID 34201116, 2021). "Ganoderma lucidum polysaccharides inhibit the proliferation of tongue cancer cells by reducing the phosphorylation of EGFR and AKT, thereby inhibiting the EGFR-mediated signaling pathway." (PMID 41059296, 2025). "The findings underscore a distinct positive response of tongue cancer to EGFR-TKI indicating its potential utility in the management of this specific type of cancer." (PMID 39863836, 2025). "In a previous study, the long non-coding RNA lnc-EGFR was shown to promote human tongue cancer proliferation via upregulation of EGFR mRNA and protein, potentially through direct binding." (PMID 35999564, 2022). "The overexpression of EGFR is commonly observed in tongue cancer and is related to the increased resistance to treatment with chemotherapeutics." (PMID 34201116, 2021). "In the present study, we showed for the first time the cytotoxic effects of DMU-214, Gef, and their combination in tongue cancer cell lines via cell cycle arrest, apoptosis induction, and inhibition of the EGFR signaling pathway." (PMID 34201116, 2021). "We showed for the first time the anti-cancer effects of DMU-214, gefitinib, and their combination in tongue cancer cells triggered via cell cycle arrest, apoptosis induction, and inhibition of the EGFR signaling pathway." (PMID 34201116, 2021). "EGFR targeting proved effective in vivo as a human tongue carcinoma xenograft mouse model showed increased tumoral uptake, enhanced PDT efficacy and prolonged anti-tumor effect of the EGFR targeted PS loaded micelles compared to untargeted micelles." (PMID 28218708, 2017). "To determine the function of RNF126 in tongue cancer development, we focused on the downstream signaling pathway of EGFR." (PMID 27227488, 2016). "The expression and activation of EGFR increased when the tongue cancer cells CAL27 were transfected with TGFBR1 and/or PTEN in siRNA." (PMID 25723392, 2015). "In contrast, our work with HN5 tongue carcinoma cells in this paper indicates that miR-7 downregulates EGFR expression at both the mRNA and protein levels." (PMID 23115635, 2012). "Antiangiogenetics, anti-EGFR, tyrosine-kinase inhibitors and proapoptotics are all factors deserving further evaluation in order to improve outcomes in patients affected by cancer of the tongue." (PMID 19696947, 2009). "It was coincidental that WSG could also suppress tongue cancer through restraining EGFR-mediated signaling pathways and promoting the apoptosis of tongue cancer cells." (PMID 37836659, 2023). "Few data are available concerning the expression and prognostic value of EGFR in tongue cancer." (PMID 19696947, 2009). "EGFR mutations are seldom found in tongue cancer and do not play a significant prognostic role; likewise, EGFR overexpression correlates with nodal stage but not DFS or OS." (PMID 19696947, 2009). "The research suggested that lidocaine with 0.4mM concentration could inhibit the EGFR by combining with EGF to generate phosphorylation and lower proliferation of corneal epithelial cells, as well as inhibit the growth of CAL27 (tongue cancer cell line) by decreasing EGFR phosphorylation." (PMID 35966857, 2022). "Initially, the investigation of the native expression profile of EGFR and EGFRP proteins in both tongue cancer cell lines was performed." (PMID 34201116, 2021). "Thus, EGFR-TKI might also be effective in patients with tongue cancer." (PMID 23592411, 2013).
tongue cancer (continued). "According to these parameters ESR1, EGFR, and BCL2 are deemed core targets within the PPI network, highlighting their significance in potential therapeutic interventions which play an important role in the treatment of tongue cancer." (PMID 39863836, 2025). "The KEGG analysis indicated the potential pathways through which bioactive compounds may exert therapeutic effects on tongue carcinoma are PI3K-Akt signaling pathway, MicroRNAs in cancer, EGFR tyrosine kinase inhibitor resistance and proteoglycans in cancer." (PMID 39863836, 2025). "Those hub genes involved in pathways of cancer are Bcl2, EGFR, ESR1, MMP9, PPARG, and MMP2 and those involved in PI3K-Akt signaling pathways are Bcl2, EGFR, CDK2, and MCL1 these genes are considered therapeutic targets for tongue cancer." (PMID 39863836, 2025).